PNPLA3 (patatin like domain 3, 1-acylglycerol-3-phosphate O-acyltransferase )
Diseases named in the same sentence as PNPLA3 in open-access papers (continued):
Sharing a sentence is not in itself a finding about the gene and the disease.
Hepatic steatosis (continued). "Another limitation was that we could not examine the association between LBP and PNPLA3 polymorphisms, which might impact the degree of hepatic steatosis." (PMID 28216979, 2017). "However, the conclusion that the presence of a PNPLA3 risk allele has no impact on development of significant liver steatosis in HIV/HCV coinfection is limited by the low patient number in this subgroup analysis." (PMID 26599080, 2015). "Interestingly, we observed that the role of the PNPLA3 genetic variants in hepatic steatosis was particularly enhanced in non-obese patients." (PMID 26139292, 2015). "Sexually-dimorphic expression of the Pnpla3 gene, which is known to be regulated by Srebp1c (but not known to be regulated by RXRα heterodimers) with a polymorphism (I148M) strongly associated with fatty liver disease, has not been reported beforehand." (PMID 23977068, 2013). "While hepatic steatosis was better discriminated by lead SNPs for HFE gene compared to hepatic iron content, the lead SNP for PNPLA3 gene showed smaller AUCs than hepatic iron content in additional analyses." (PMID 40691542, 2025). "Overall, these data suggest that LD targeting of PNPLA3 I148M and the interaction with ABHD5 is required to promote liver steatosis." (PMID 39814233, 2025). "Thus, PNPLA3 rs738409 may predict better hepatic steatosis outcomes after MBS." (PMID 39125390, 2024). "Patatin-like phospholipase domain-containing 3 (PNPLA3), also known as adiponutrin (ADPN), is one of the most studied genes in relationship to hepatic steatosis and NAFLD progression." (PMID 37241000, 2023). "Interestingly, although a clear association exists between MAFLD-related hepatic steatosis and IR, some genetically determined forms of fatty liver (such as a sequence variation within the ‘patatin-like phospholipase domain-containing protein 3′ [PNPLA3] gene) do not associate with IR." (PMID 37367914, 2023). "Therefore, the effects of EPI-001 on hepatic steatosis may be associated with SREBP-1c and PNPLA-3." (PMID 36555703, 2022). "By using this model, in the present work we show that BemA treatment alleviates hepatic steatosis by several mechanisms, including reduced KHK expression, PNPLA3 induction, and PPAR⍺ activation." (PMID 35884822, 2022). "Although PNPLA3 and TM6SF2 appear to be the most prominent hepatic steatosis determinants across the population, additional genetic deficiencies, which have been relatively infrequent or less significant, have been shown to produce fatty liver metabolism." (PMID 36557278, 2022). "However, we also need to emphasize that liver fat content is high but insulin resistance and the risk of diabetes are not in patients with fatty liver disease with a strong hepatic genetic component (ie, the 148Met allele in PNPLA3 and the 167Lys allele in TM6SF2)." (PMID 35615717, 2022). "However, this hypothesis is in sharp contrast to the phenotype of PNPLA3-deficient mice, which show no signs of fatty liver disease, whereas the overexpression of defective PNPLA3 variants (p.Iso148Met or p.Ser47Ala) leads to hepatic steatosis in mice." (PMID 36355098, 2022). "Indeed, p.I148M overexpression raised hepatic TG concentrations in wt, but not in Cgi-58 knock-out (KO) mice, indicating that the PNPLA3 mutation may prompt hepatic steatosis, hindering ATGL/PNPLA2 activity on LDs in a CGI-58-dependent manner." (PMID 34680476, 2021). "Furthermore, a study evaluating the combined effect of PNPLA3 and TM6SF2 polymorphisms in NAFLD found variants of PNPLA3 and TM6SF2 to be independently associated with hepatic steatosis, while PNPLA3 but not TM6SF2 was associated with liver fibrosis in a multivariable model." (PMID 34076851, 2021). "Our findings here with MBOAT7-driven restructuring of the lipid droplet surface, and those recently published with PNPLA3, suggest that alterations in lipid modifying enzyme access to the surface of cytosolic lipid droplets may be a common mechanism by which human fatty liver develops." (PMID 31621579, 2019).
Hepatic steatosis (continued). "Thus, PNPLA3 genotyping might become a test to characterize patients with NAFLD, however more studies are needed to clarify how this variant affects the development of fatty liver disease." (PMID 31428049, 2019). "Moreover, genetic polymorphisms, such as Patatin-like phospholipase domain-containing protein 3 (PNPLA3), transmembrane 6 superfamily member 2 gene (TM6SF2) and membrane bound O-acyltransferase domain containing 7 gene (MBOAT7), are also associated with hepatic steatosis and fibrosis." (PMID 29874807, 2018). "The regression coefficients of PNPLA3 rs738409 and TM6SF2 rs58542926 were essentially unchanged upon adjustment for measured hepatic steatosis, ALT or ferritin but attenuated after inclusion of features of the metabolic syndrome." (PMID 26847197, 2016). "The association of PNPLA3 148M allele with HOMA-IR in HCV infected subjects supports the hypothesis that insulin resistance may be interpreted as a consequence rather than a cause of hepatic steatosis." (PMID 22978414, 2012). "Although many cross-sectional studies have investigated the relationship between PNPLA3 rs738409, fatty liver, and fibrosis, few cohort studies have been conducted in healthy individuals without fatty liver." (PMID 40074353, 2025). "This study investigated the effects of PNPLA3 rs738409 on liver fat and fibrosis over time in a general population without fatty liver disease, including its involvement in the gut microbiota." (PMID 40074353, 2025). "Moreover, abolishing the LD binding of PNPLA3 I148M prevented the interaction with ABHD5 and liver steatosis." (PMID 39814233, 2025). "Neither whole body deletion nor overexpression of wildtype PNPLA3 in mice results in hepatic steatosis, suggesting that PNPLA3 I148M is not a simple loss of function, but rather a gain of function mutation." (PMID 38247511, 2024). "Also, as the severity of hepatic steatosis in MASLD increases, PNPLA3 rs738409 C>G CG and GG genotype carriers in subjects had higher proportions than CC genotype carriers (p = 0.001)." (PMID 38674389, 2024). "Certain polymorphisms in PNPLA3 and LYPLAL1 are known to induce hepatic steatosis without the presence of common metabolic characteristics such as insulin resistance and obesity in patient groups." (PMID 37363524, 2023). "However, in mice fed with a NASH-inducing diet, it reduced the liver steatosis index (LSI) and the NAFLD activity score (NAS) independently of the PNPLA3 genotype." (PMID 37241000, 2023). "The authors concluded that when IL-32 is overexpressed, independent of PNPLA3 genotype, it significantly correlated with increased hepatic steatosis and significant fibrosis." (PMID 35036892, 2022). "Genotyping of PNPLA3 in 68 patients showed that the difference between subjects without steatosis and subjects with hepatic steatosis was due to the higher frequency of genotype GG." (PMID 34833467, 2021). "In a study that included 117 patients treated with DAAs and evaluated using transient elastography for hepatic fibrosis and controlled attenuation parameters for hepatic steatosis, PNPLA3 genotype was not correlated with the degree of hepatic steatosis." (PMID 34833371, 2021). "Patatin-like phospholipase domain-containing protein 3 (PNPLA3) has been linked to the development and evolution of fatty liver but not to insulin resistance." (PMID 34833467, 2021). "Surprisingly, Pnpla3 gene knockout mice have normal levels of plasma and hepatic triglyceride contents and they do not develop fatty liver disease." (PMID 31921875, 2019). "The Pnpla3 deletion in mice does not affect liver TAG content even under high-sucrose or high-fat diet conditions and human PNPLA3 overexpression in mice does not decrease liver steatosis." (PMID 27757845, 2017).
Hepatic steatosis (continued). "Compared with men without fatty liver, those with fatty liver were more likely to be non-Hispanic white and have PNPLA3 non-CC genotype and had higher median BMI, greater abdominal VAT and SAT, higher HOMA-IR scores, and higher triglyceride levels." (PMID 28929125, 2017). "The mice models with either knockout PNPLA3 or overexpression of the wild-type PNPLA3 did not lead to fatty liver." (PMID 27744419, 2016). "Another study confirmed these findings in HIV monoinfected patients showing a strong correlation between PNPLA3 non-C/C genotype and hepatic steatosis." (PMID 26599080, 2015). "The odds ratios further increased compared with those in the whole population, and the PNPLA3 genotype was the strongest predictor for hepatic steatosis in non-obese subjects." (PMID 26139292, 2015). "In contrast, the PNPLA3 SNP did not independently determine hepatic steatosis in overweight or obese patients." (PMID 26139292, 2015). "Interestingly, adiposity augments the effects of PNPLA3 I148M and TM6SF2 E167K mutations on fatty liver disease without affecting other adiposity-related parameters, suggesting a diet–gene interaction." (PMID 38247511, 2024). "The causes and consequences of hepatic steatosis and inflammation in NASH patients may differ between PNPLA3 I148M carriers and those without the variant." (PMID 36035124, 2022). "Finally, the gene polymorphisms including TM6SF2/PNPLA3/MBOAT7 which are highly related to the abnormal metabolic disease and fatty liver disease are not evaluated in our study." (PMID 35186751, 2022). "However, these modification in hepatic DAG composition has been not supported by Franko and colleagues, who corroborated the notion that PNPLA3 variation is strictly correlated with fatty liver, but not with IR, whereby uncoupling these two NAFLD features." (PMID 34680476, 2021). "To our knowledge, we are the first to report that PNPLA3 genotype may not modify the relationship between dietary intake and hepatic steatosis in MO adults with overweight or obesity." (PMID 34280991, 2021). "Despite the strong association of PNPLA3 with human NAFLD/NASH and other liver disease, Pnpla3−/− mice showed no phenotype, including differences in TG hydrolysis, energy/glucose/lipid homoeostasis or hepatic steatosis/injury after high-fat diet (HFD) challenge." (PMID 33672787, 2021). "Moreover, antisense oligonucleotides-mediated silencing of Pnpla3 reduces liver steatosis in homozygous Pnpla3 148M/M knock-in mutant mice, but not in wild-type littermates fed a steatogenic high-sucrose diet." (PMID 32957701, 2020). "The lack of association of MARC1 p.A165T and HSD17B13 rs72613567 with CAD (in contrast to PNPLA3 and TM6SF2) suggests that pharmacologic treatment of cirrhosis and hepatic steatosis may not universally cause excess cardiovascular risk." (PMID 32282858, 2020). "However, the role of PNPLA3 SNPs in patients with concurrent chronic hepatitis B and hepatic steatosis has not been well explored." (PMID 28695131, 2017). "Here, we investigated the PNPLA3 polymorphisms in biopsy-proven chronic hepatitis B patients with (CHB+HS group, n = 52) or without hepatic steatosis (CHB group, n = 47) and non-CHB subjects with (HS group, n = 37) or without hepatic steatosis (normal group, n = 45)." (PMID 28695131, 2017). "Likewise, chronic overexpression of PNPLA3-I148M (but not PNPLA3-I148) in mice leads to hepatic steatosis." (PMID 29286303, 2017). "When comparing patient groups with different PNPLA3-genotype, we could not find a difference in the prevalence of hepatic steatosis across the groups." (PMID 26599080, 2015). "However, this was soon refuted as the PNPLA3 KO mice did not develop hepatic steatosis." (PMID 40589542, 2025). "Thus, while we described an inverse interaction effect between PNPLA3 genotypes HOMAIR and TG in predicting the higher risk of hepatic steatosis, the modest sample size could be the reason why we did not identified synergy with BMI37." (PMID 29487372, 2018).
Hepatic steatosis (continued). "Moreover, the expression of recombinant isoforms of PNPLA3 that retained enzymatic activity but lacked lysine residues, and hence resisted ubiquitination, resulted in the accumulation of the protein and development of hepatic steatosis in a transgenic mouse model." (PMID 39000384, 2024). "Our investigation found that some of the changes in differentially expressed genes involved with hepatic steatosis, such as the farnesyl X receptor (FXR) and PNPLA3, were only altered by proglumide and not by genetic knockout of the CCK-BR." (PMID 38252699, 2024). "Genetic factors, including patatin-like phospholipase domain-containing protein 3 (PNPLA3) and transmembrane 6 superfamily member 2 (TM6SF2) affect liver steatosis with or without dyslipidemia." (PMID 30576386, 2018). "Liver steatosis—as assessed by CAP—was comparable between patients with PNPLA3 C/C and PNPLA3 non-C/C patients (215.5±59.7 vs. 203.5±41.9dB/m; p = 0.56)." (PMID 26599080, 2015). "However, Pnpla3−/− mice do not display a fatty liver phenotype, whereas PNPLA3I158M knockin mice develop hepatic steatosis, illustrating the complexity of the regulatory roles of PNPLA3 in hepatic lipid metabolism." (PMID 33086624, 2020).
steatosis (203 papers, 2012 to 2026). Increased lipid within the cytoplasm of cells. "Human fetal hepatocyte organoids model NAFLD steatosis under three triggers: fatty acid overload, PNPLA3 I148M mutation, and APOB/MTTP mutations." (PMID 40475995, 2025). "Among the five steatosis‐associated genetic variants evaluated, PNPLA3 I148M consistently exhibited the highest discriminative ability." (PMID 40478199, 2025). "The homozygous PNPLA3 rs738409[G] has been associated with a picture of zone 1-dominant steatosis and an increase in portal inflammation, as well as associated with a greater risk of evolution to fibrosis and cirrhosis, regardless of the presence of obesity." (PMID 41311807, 2025). "In prediction models for the identification of liver fat content by magnetic resonance proton density fat fraction (MR‐PDFF), carriage of PNPLA3 risk allele was identified as causing 8.7% higher steatosis." (PMID 39412170, 2025). "PNPLA3 genetic variants have influence over the status of liver diseases, ranging from simple steatosis to MASLD, MASH, cirrhosis, and HCC." (PMID 40507973, 2025). "This difference indicates that the imaging signatures associated with PNPLA3 I148M are likely reflecting a unique pattern of hepatic fat distribution, which are more prominent in individuals with steatosis." (PMID 40478199, 2025). "The rs2294918, another SNP in PNPLA3, is associated with reduced expression of the PNPLA3 protein, lowering the effect of the rs738409: G variant on predisposition to steatosis and liver damage." (PMID 40806538, 2025). "The PNPLA3-I148M variant, strongly linked to steatosis and fibrosis, highlights another genetic target." (PMID 40002806, 2025). "The PNPLA3 polymorphism has been documented from genome-wide association studies as increased steatosis susceptibility and is currently the most robust genetic determinant in MASLD." (PMID 40002828, 2025). "We examined the specific impact of the PNPLA3 rs738409 GG variant on steatosis, cytokine secretion, stellate cell activation, and fibrosis over an 8-day time course using previously published media formulated to recapitulate MASLD phenotypes." (PMID 39324073, 2024). "Further studies have shown that ubiquitylation and proteasome-mediated Pnpla3 degradation were impaired by the I148M substitution, leading to the accumulation of mutated Pnpla3 in LDs and enhancing steatosis." (PMID 38665220, 2024). "A nonsynonymous variant in PNPLA3 has been associated with steatosis, steatohepatitis and hepatic fibrosis and its deregulation can lead to increased hepatocellular triglyceride accumulation, impairing lipid remodeling and turnover and development of NAFLD." (PMID 38365720, 2024). "Our screen showed that inhibitors of Src, PI3K, and Akt can reduce lipid accumulation in a dose-dependent manner when steatosis is induced by PNPLA3 mutations." (PMID 39000384, 2024). "Consistent with previous studies, we detected a strong association with PNPLA3 rs3747207 polymorphism, a gene that has been independently associated with steatosis and fibrosis accumulation in various types of liver conditions." (PMID 39858580, 2024). "We then evaluated genotype-specific effects on steatosis using fluorescence imaging to quantify LipidTOX staining in the PNPLA3 GG variant and CC wild-type LAMPS that were maintained for 8 days in EMS-containing resmetirom (1 μM) or vehicle control." (PMID 39324073, 2024). "Previous studies haveshown that overexpression of wild-type proteins (PNPLA3) in mice doesnot cause steatosis." (PMID 38990186, 2024). "We observed increased steatosis, immune activation, stellate cell activation, and secretion of pro-fibrotic markers in the PNPLA3 GG variant compared to the wild-type CC LAMPS, consistent with the clinical characterization of this variant." (PMID 39324073, 2024).